FKRP (fukutin related protein)
Diseases named in the same sentence as FKRP in open-access papers (continued):
Sharing a sentence is not in itself a finding about the gene and the disease.
muscular dystrophies (continued). "More recently, Dhoke and colleagues documented a universal gene correction approach for fukutin-related protein (FKRP), whose mutations are associated with a broad spectrum of muscular dystrophies, including LGMD type 2I (LGMD2I/R9) and the severe Walker-Warburg syndrome (WWS)." (PMID 35802202, 2022). "Also, there were no CNVs detected in the targeted analysis of SGCA, SGCB, SGCG, SGCD, and FKRP genes for other frequent limb-girdle muscular dystrophies." (PMID 36425804, 2022). "Interestingly, missense mutations in FKRP that cause LGMD2I also show reduced expression of matriglycan and exhibit a milder muscular dystrophy." (PMID 32975514, 2020). "Despite advances in understanding the pathophysiology of FKRP-associated myopathies, clinical research in the limb-girdle muscular dystrophies has been limited by the lack of normative biomarker data to gauge disease progression." (PMID 32429923, 2020). "The results provide a proof of concept for future clinical trials in patients with FKRP-related muscular dystrophy and demonstrate that AAV-mediated gene therapy can potentially benefit patients at all stages of disease progression, but earlier intervention would be highly preferred." (PMID 28480302, 2017). "To further validate the utility of iMyoblasts for muscle disease research, we investigated the potential ex vivo and in vivo modeling applications of iMyoblasts from iPSCs derived from patients with FKRP dystroglycanopathies and LGMDR7 muscular dystrophy." (PMID 35076017, 2022). "The dataset includes 13 muscular dystrophy related phenotypes, i.e. ALS, AQM, BMD, Calpain3, DMD, Dysferlin, Lamin A/C, Emerin, FKRP, FSHD, HSP, JDM, and NHM." (PMID 18801195, 2008). "Thus, our results reveal that FKRP simultaneously regulates the two major muscle-ECM linkages essential for fibre survival, and establishes a new disease axis for the muscular dystrophies." (PMID 34012031, 2021).
Walker-Warburg syndrome (17 papers, 2007 to 2025). "Mutations in FKRP can cause a range of phenotypes, including MDC1C (a severe congenital muscular dystrophy), Walker-Warburg syndrome, muscle-eye-brain disease, a severe form of limb-girdle muscular dystrophy type 2I (LGMD2I), and a mild form of LMGD2I." (PMID 18036232, 2007). "Mutations in the fukutin-related protein (FKRP) cause Walker-Warburg syndrome (WWS), a severe form of congenital muscular dystrophy." (PMID 33513091, 2021). "Mutations in FKRP are also associated with Congenital Muscular Dystrophy (MDC1C), Walker-Warburg Syndrome (WWS) and Muscle Eye Brain disease (MEB)." (PMID 21886772, 2011). "The Global FKRP Registry is a database for individuals with conditions caused by mutations in the Fukutin‐Related Protein (FKRP) gene: limb girdle muscular dystrophy R9 (LGMDR9, formerly LGMD2I) and congenital muscular dystrophies MDC1C, Muscle–Eye–Brain Disease and Walker–Warburg Syndrome." (PMID 32342672, 2020).
congenital muscular dystrophy (15 papers, 2007 to 2025). A muscular dystrophy that is characterized by diminished muscle tone (hypotonia), progressive muscle weakness and degeneration (atrophy), abnormally fixed joints, spinal rigidity, and delays in reaching motor milestones such as sitting or standing unassisted. "FKRP mutations manifest a wide range of disease severity from severe congenital muscular dystrophy (CMD), Walker-Warburg syndrome (WWS), and muscle-eye-brain (MEB) disease to mild limb girdle muscular dystrophy (LGMD) 2I/R9." (PMID 40833945, 2025). "Mutations in the fukutin-related protein gene (FKRP) result in two distinct allelic diseases: severe congenital muscular dystrophy and LGMD2I." (PMID 25135358, 2014). "Mutations in FKRP were originally reported to cause MDC1C, a severe form of congenital muscular dystrophy, however, later it has become clear that mutations in the FKRP gene might cause a wider range of phenotypes such as those of LGMD2I, MEB and WWS." (PMID 21886772, 2011).
limb-girdle muscular dystrophy (15 papers, 2016 to 2025). Limb-girdle muscular dystrophy (LGMD) is a heterogeneous group of muscular dystrophies characterized by proximal weakness affecting the pelvic and shoulder girdles. "Pathogenic variants in the FKRP gene cause impaired glycosylation of α-dystroglycan in muscle, producing a limb-girdle muscular dystrophy with cardiomyopathy." (PMID 32429923, 2020). "A relevant dysregulation has been proposed in limb-girdle muscular dystrophies (LGMD) related to mutations in FKRP (LGMD2I/LGMD R9), as well as in CAV3 (LGMD1C/RMD2)." (PMID 32823799, 2020). "For instance, another DCM-hiPSC model was obtained from patients harboring a fukutin-related protein gene mutation (826C > A; Leu276Ile, transmembrane protein) associated to Limb-Girdle muscular dystrophy (LGMD) and was studied at comparable levels of maturation." (PMID 32477154, 2020). "FKRP mutations are responsible for LGMDR9, a form of autosomal recessive Limb-Girdle Muscular Dystrophy." (PMID 37887288, 2023). "In this study, we further phenotyped the P448Lneo− mouse model of FKRP-related limb girdle muscular dystrophy." (PMID 29625576, 2018). "Limb-girdle muscular dystrophy (LGMD) is a progressive muscle weakness affecting the pelvic and shoulder girdles, primarily caused by mutations in proteins like myotilin, lamin, caveolin-3, calpain-3, dysferlin, γ-sarcoglycan, TCAP, TRIM32, FKRP, and titin." (PMID 39415830, 2024). "Furthermore, since 1-me-Nam is prone to urinary secretion, it may be a useful indicator of efficacy for oligonucleotide-based therapeutics, such as those being tested in the FKRP mutant model of limb-girdle muscular dystrophy." (PMID 33092650, 2020). "In the subjects with CK ≥ 2000 U/l without DMD mutations, the most common limb-girdle muscular dystrophy (LGMD) genes were investigated and mutations in DYSF, SGCB and FKRP genes were found." (PMID 32112218, 2020). "For these individuals, mutation analysis was extended to include the seven most common limb-girdle muscular dystrophy (LGMD) genes (DYSF, CAPN3, SGCA, SGCB, SGCC, SGCD, and FKRP)." (PMID 31588416, 2017). "Genetic screening for limb-girdle muscular dystrophy (LGMD) hotspot mutations (SGCG, FKRP, and CAPN3 genes) was negative." (PMID 40217903, 2025). "Further molecular genetic testing at age 9 for polyneuropathy, FSHD (facioscapulohumeral muscular dystrophy), and LGMD (limb-girdle muscular dystrophy) was negative (targeted testing of the CAPN3, FKRP and PMP22 genes was performed)." (PMID 36361862, 2022).
dilated cardiomyopathy (7 papers, 2011 to 2022). Cardiomyopathy which is characterized by dilation and contractile dysfunction of the left and right ventricles. "The FKRP p.[Leu276Ile]; [Asn463Asp] genotype is reported for the first time in Mexican patients as being associated with dilated cardiomyopathy." (PMID 31671740, 2019). "Genetic variants in the FKRP gene cause a broad spectrum of phenotypes in LGMDR9 patients, ranging from mild muscle weakness and atrophy to more severe symptoms, with loss of ambulation, dilated cardiomyopathy, and respiratory and mental impairment." (PMID 35740450, 2022). "It is possible that more prominent defects such as dilated cardiomyopathy could emerge in later stage of the FKRP mutant mice." (PMID 27711214, 2016). "Patients with dilated cardiomyopathy and no or minimal muscle involvement were reported with mutations in fukutin (FKTN,) and fukutin-related protein (FKRP,), showing reduced laminin binding capacity of alpha-dystroglycan in heart muscle biopsies." (PMID 22242004, 2011).
limb-girdle muscular dystrophy type 2I (6 papers, 2007 to 2024). "Here, we report the safety and effects of oral ribose supplementation during 6 months in a patient with limb girdle muscular dystrophy type 2I (LGMD2I) due to a homozygous FKRP mutation." (PMID 38736632, 2024). "Limb-girdle muscular dystrophy type 2I (LGMD2I) was molecularly characterized in 2001 as caused by mutations in the gene for fukutin-related protein (FKRP)." (PMID 21970816, 2011). "Loss-of-function mutations in the Fukutin-related protein (FKRP) gene cause limb-girdle muscular dystrophy type 2I (LGMD2I) and other forms of congenital muscular dystrophy-dystroglycanopathy that are associated with glycosylation defects in the α-dystroglycan (α-DG) protein." (PMID 28480302, 2017). "Patients with FKRP variants have several phenotypes, including limb-girdle muscular dystrophy type 2I (LGMD2I), muscle–eye–brain disease and Walker-Warburg syndrome." (PMID 32351701, 2020).
Becker muscular dystrophy (4 papers, 2007 to 2020). Becker muscular dystrophy (BMD) is a neuromuscular disease characterized by progressive muscle wasting and weakness due to degeneration of skeletal, smooth and cardiac muscle. "Becker muscular dystrophy (BMD) due to mutations in DMD and limb-girdle muscular dystrophy 2I (LGMD2I) due to mutations in FKRP (OMIM#606596) are the most common dystrophies to present with RM." (PMID 25929793, 2015). "Chan also reported an increased risk of RM in patients with some hereditary neuromuscular diseases, such as Duchenne muscular dystrophy (DMD)/Becker muscular dystrophy (BMD), fukutin-related protein, dysferlin, γ-sarcoglycans, and anoctamin 5 deficiency-associated muscular atrophy." (PMID 33014933, 2020).
cardiomyopathy (4 papers, 2018 to 2024). A disease of the heart muscle or myocardium proper. "One study suggested that individuals homozygous for the common c.826C>A FKRP mutation are at greater risk of developing cardiomyopathy than those with compound heterozygous mutations, while other studies proposed the reverse relationship." (PMID 38791328, 2024). "Systemic delivery to FKRPL276I mice at multiple ages rendered body-wide FKRP protein expression and restored glycosylation of α-DG in both skeletal and cardiac muscles, thereby ameliorating the dystrophic pathology and cardiomyopathy." (PMID 30417025, 2018).
Muscular dystrophy-dystroglycanopathies (3 papers, 2018 to 2022). "Muscular dystrophy-dystroglycanopathies (MDDGs) resulting from fukutin-related protein (FKRP) gene mutations are rare disorders that result in a wide spectrum of clinical severity based on the age of onset, the degree of myogenic atrophy, and/or neurologic involvement." (PMID 30417025, 2018).
calpainopathy (2 papers, 2007 to 2020). "It is becoming increasingly clear that LGMD2I, caused by mutations in FKRP, is one of the more common LGMDs, possibly rivaling LGMD2A (calpainopathy) in prevalence." (PMID 18036232, 2007).
dystrophinopathies (2 papers, 2019 to 2024). "The results obtained show that the Duchenne/Becker-like phenotype is frequently determined by mutations in the FKRP gene in our cohort and highlight the importance of considering LGMDR9 in the differential diagnosis of dystrophinopathies in Calabria." (PMID 39408683, 2024).
muscle disorders (2 papers, 2018 to 2020). "Our data show robust engraftment that is accompanied by restoration of α-DG functional glycosylation and amelioration of disease phenotypes, thus supporting the therapeutic benefit of cell transplantation for LGMD2I and potentially other FKRP-associated muscle disorders." (PMID 32321586, 2020).
congenital muscular dystrophy 1C (1 paper, 2025). "In addition, different knockdown fkrp models were studied to understand Walker–Warburg syndrome (WWS), LGMDR9, and congenital muscular dystrophy 1C (MDC1C), which share different mutations in the FKRP gene." (PMID 41009401, 2025).
epilepsy (1 paper, 2024). A brain disorder characterized by episodes of abnormally increased neuronal discharge resulting in transient episodes of sensory or motor neurological dysfunction, or psychic dysfunction. "Evaluating the epilepsy and CMAR panels revealed 5 P/LP variants in genes that generally associate with homozygous recessive inheritance (QARS, CLN8, PPT1, CSTB, and FKRP) in heterozygous decedents, indicating that these are likely incidental findings." (PMID 38229148, 2024).
glioblastoma (1 paper, 2025). The most malignant astrocytic tumor (WHO grade IV). "Furthermore, we validated the splicing variants of FKRP using primers targeting different exonic regions in the human glioblastoma cell line SH-SY5Y and the corresponding mouse cell line N2A." (PMID 40288647, 2025).
progressive muscular dystrophy (1 paper, 2014). "Largemyd mice and knock-in mice carrying the FKRP P448L mutation show no detectable amounts of functionally glycosylated α-DG, no laminin binding activity, and progressive muscular dystrophy." (PMID 25198651, 2014).
thyroid cancer (1 paper, 2020). "The relationship between thyroid cancer in this patient and the FKRP variants could not be explained." (PMID 32351701, 2020).
weakness (1 paper, 2024). "In Austria, the most frequent cause of limb-girdle muscular weakness and hereditary myopathy were pathogenic variants in CAPN3, FKRP, ANO5, DYSF, SGCA." (PMID 38758368, 2024).
myopathies (4 papers, 2016 to 2022). "For probands A1, A2, and B6, we previously found mutations in myopathy-related genes in FKRP, LMNA, and CCDC78, respectively." (PMID 34720847, 2021).
Respiratory disease (1 paper, 2018). "Respiratory disease is seen in the clinical spectrum of FKRP-mediated LGMD." (PMID 29625576, 2018).
–Brain diseases (1 paper, 2024). "Pathogenic variants localized in the gene coding for the Fukutin-Related Protein (FKRP) are responsible for Limb-Girdle Muscular Dystrophy type 9 (LGMDR9), Congenital Muscular Dystrophies type 1C (MDC1C), Walker–Warburg Syndrome (WWS), and Muscle–Eye–Brain diseases (MEBs)." (PMID 39408683, 2024).
FKRP also shares sentences with these, for which no sentence is quoted: muscle-eye-brain disease (5 papers); Duchenne muscular dystrophy (3); dysferlinopathy (2); facioscapulohumeral muscular dystrophy (2); Hydrocephalus (2); Miyoshi myopathy (2); Myotonic Dystrophies (2); sarcoglycanopathies (2); amyotrophic lateral sclerosis (1); Autoimmunity (1); cancer (1); cardiac failure (1); Cerebellar hypoplasia (1); cobblestone lissencephaly (1); dermatomyositis (1); distal myopathy (1); Emery-Dreifuss muscular dystrophy (1); genetic diseases (1); hereditary spastic paraplegia (1); Huntington disease (1); Intellectual disability (1); iris coloboma (1); Lissencephaly (1); MELAS (1); neuroblastoma (1); neuromuscular disease (1); neuropathy (1); polymicrogyria (1); polyneuropathy (1); Pompe disease (1).
A further 7 diseases each share a sentence with FKRP in 1 paper.